STC2 (stanniocalcin 2)
Diseases named in the same sentence as STC2 in open-access papers (continued):
Sharing a sentence is not in itself a finding about the gene and the disease.
colon cancer (11 papers, 2016 to 2023). "Another study revealed STC2 can be induced in human colon cancer cells upon selenomethionine treatment, which is supposed to deprive intracellular cysteine or sulfhydryl sources." (PMID 35501821, 2022). "The STC2 also regulates the growth and migration of colon cancer cells under hypoxic conditions and reduces patients’ response to certain chemotherapeutic drugs." (PMID 35096084, 2022). "cDNA microarray revealed bevacizumab induces STC2 expression through activating HIF-1 signaling in orthotopic human colon cancer xenografts." (PMID 35501821, 2022). "Increased STC2 expression induced by anti-vascular endothelial growth factor antibody therapy was observed in colon cancer, whereas the role of STC2 is still unclear." (PMID 34737677, 2021). "STC2 has recently been reported as an independent prognostic biomarker, whose expression is related to colon cancer progression." (PMID 32788867, 2020). "Our findings support STC2-mediated EMT process is associated with colon cancer occurrence and development, which gives a new insight on biotherapy of colon cancer by preventing progression of EMT through silencing STC2 expression." (PMID 27662663, 2016). "In conclusion, we elucidated the linkage of STC2 with colon cancer development in vitro and in vivo." (PMID 27662663, 2016). "On contrary, knockdown of STC2 under hypoxic conditions reverses migration of colon cancer." (PMID 32296395, 2020). "Additionally, the clinical colon cancer tissues and patient serum analysis were further supported that higher level of STC2 protein is present in colorectal tumor and patient's serum compared with normal samples, which also has linkage with tumor pathologic classification and CRC patient survival." (PMID 27662663, 2016). "qRT-PCR was performed from RNA extracted from 43 pairs of colon cancer and adjacent normal tissues to observe the relative expression levels of eight GRGs (P4HA1, STC2, CHPF2, PMM2, PGM2, ENO3, PPARGC1A, and PPP2CB)." (PMID 34422808, 2021). "In this study, our findings indicate STC2 not only activates normal colon mucosal epithelial cells to acquire EMT features, and it also promotes colon cancer cell invasion and migration via ERK/MEK and PI3K/AKT signaling pathways." (PMID 27662663, 2016). "Therefore, the biological functions of STC2 in EMT process and colon cancer development deserve to further explore in detail." (PMID 27662663, 2016).
pancreatic cancer (9 papers, 2019 to 2024). "STC2 has been reported to be significantly stimulated under ER stress and to promote metastasis in pancreatic cancer." (PMID 36727081, 2022). "In pancreatic cancer, STC2 expression was positively correlated with tumor size and lymph node metastasis and negatively correlated with 5 years survival rate studied in 98 case samples." (PMID 32296395, 2020). "Given the close correlation between STC2 expression and clinicopathological factors, the prognosis of pancreatic cancer patients was analyzed by survival curve analysis." (PMID 32258098, 2019). "Our data demonstrated that STC2 was a potential prognostic biomarker and therapeutic target for pancreatic cancer." (PMID 32258098, 2019). "This is the first study to show that elevated expression of STC2 acted as a tumor promoter in pancreatic cancer cell." (PMID 32258098, 2019). "Consistently, the result of IHC showed that the protein expression of STC2 was remarkably upregulated in tumors as compared to the normal tissues, to further study the significance of STC2 in the development of pancreatic cancer." (PMID 32258098, 2019). "The aberrant expression was significantly correlated with the development of pancreatic carcinoma, indicating that STC2 was a potential biomarker for diagnosis of pancreatic cancer." (PMID 32258098, 2019). "This study showed that the expression of STC2 was significantly upregulated in pancreatic cancer tissues." (PMID 32258098, 2019). "Further results showed that STC2 modulated the invasion and migration of pancreatic cancer cells, suggesting a robust role of STC2 in this cancer." (PMID 32258098, 2019). "Consistently, the wound healing assay showed that upregulation of STC2 elevated the migration activity of pancreatic cancer cells, while inhibition of STC2 downregulated the migration rate." (PMID 32258098, 2019). "Given the evidence linking STC2 to tumor metastasis, the involvement of STC2 in the process of EMT was determined and we demonstrated that STC2 markedly induced an EMT transition in pancreatic cancer cells." (PMID 32258098, 2019). "The mRNA expression level of STC2 in pancreatic tumors was significantly elevated as compared to the surrounding normal tissues." (PMID 32258098, 2019). "In addition, STC2 can promote the proliferation of pancreatic cancer cells by promoting epithelial‐mesenchymal transition (EMT) of pancreatic cancer cells." (PMID 39428922, 2024). "Furthermore, overexpression of STC2 promoted the proliferation, migration, and invasion of pancreatic cancer by inducing epithelial–mesenchymal transition." (PMID 32296395, 2020). "We first determined the expression level of STC2 in pancreatic cancer, and the results showed that its expression had a good correlation with clinicopathological parameters, suggesting that STC2 was a potential biomarker for the diagnosis of pancreatic cancers." (PMID 32258098, 2019). "As shown by in vitro study, STC2 was involved in the regulation of pancreatic cancer proliferation." (PMID 32258098, 2019). "The results showed that overexpression of STC2 could increase the invasion rate, while knocking down of STC2 decreased the invasion activity of pancreatic cancer cells." (PMID 32258098, 2019). "Further mechanistic investigations revealed that the expression of STC2 could significantly promote the epithelial–mesenchymal transition (EMT) in pancreatic cancer cells." (PMID 32258098, 2019). "Furthermore, overexpression of STC2 could promote the proliferation, migration, and invasion of pancreatic cancer cell lines, while knocking down of STC2 led to antiproliferation and antimetastasis activities." (PMID 32258098, 2019). "Therefore, in this study, we confirmed the significance of STC2 expression in pancreatic carcinoma." (PMID 32258098, 2019).
pancreatic cancer (continued). "Another controversy is related to the STC2 gene, which is also upregulated in the responders, while other studies indicate that STC2 is a positive regulator of metastasis and poorer prognosis in HNSCC and pancreatic cancer." (PMID 35875133, 2022). "STC2 shows significant upregulation in pancreatic cancer tissues and contributes to metastasis by promoting EMT in pancreatic cancer." (PMID 33952718, 2021). "This study showed that overexpression of STC2 in pancreatic cancer contributed to the metastasis by promoting EMT, suggesting that STC2 could be a potential prognostic biomarker and therapeutic target for pancreatic cancer." (PMID 32258098, 2019). "However, the significance of STC2 expression has not been reported in pancreatic cancer." (PMID 32258098, 2019).
prostate carcinoma (8 papers, 2014 to 2024). A carcinoma that arises from epithelial cells of the prostate gland. "Knockdown of STC2 compromises the colony formation; while ectopic expression of STC2 promotes cell proliferation, indicating STC2 may serve as a novel diagnostic biomarker for aggressive prostate cancer and a new therapeutic target for CRPC." (PMID 35501821, 2022). "The analysis of sequences in the 5ʹ upstream region of STC2, a gene known to promote prostate cancer proliferation, revealed that the combination treatment induced at least a slight increase in DNA methylation (40%) compared with the controls (35%)." (PMID 39766901, 2024). "CRPC cells show increased STC2 mRNA levels relative to those from castration-naïve prostate cancer cells." (PMID 35501821, 2022). "In fact, STC2 is among the most upregulated genes in hormone insensitive prostate cancer cells treated with pigment epithelium-derived factor, but the roles of STC2 in CRPC and its potential as a therapeutic target remain unclear and require further investigation." (PMID 35501821, 2022). "Therefore, STC2 might serve as a novel biomarker for the diagnosis and treatments of aggressive prostate cancer." (PMID 34612765, 2021). "Nevertheless, high-level evidence is still lacking to verify the potential of STC2 in prostate cancer." (PMID 34612765, 2021). "STC2 was not expressed in normal prostate tissues and indolent castration-naïve prostate cancers." (PMID 34612765, 2021).
esophageal cancer (7 papers, 2012 to 2022). A primary or metastatic malignant neoplasm involving the esophagus. "Further studies are needed to elucidate the exact roles of STC1 and STC2 in hypoxia and in progression of esophageal cancer." (PMID 22200953, 2012). "One study investigated the expression of STC2 in 70 esophageal cancer cell lines." (PMID 35945754, 2022). "STC2 was over-expressed in tumors such as colon adenocarcinoma (COAD), esophageal carcinoma (ESCA), glioblastoma multiforme (GBM) and HNSC, etc. and under-expressed in acute myeloid leukemia (LAML) and skin cutaneous melanoma (SKCM)." (PMID 34475994, 2021).
esophageal squamous cell carcinoma (7 papers, 2014 to 2024). Esophageal squamous cell carcinoma (ESCC) is a type of esophageal carcinoma (EC) that can affect any part of the esophagus, but is usually located in the upper or middle third. "STC2 is a risk gene significantly associated with OS in patients with esophageal squamous cell carcinoma." (PMID 36685853, 2022).
glioblastoma (7 papers, 2014 to 2024). The most malignant astrocytic tumor (WHO grade IV). "We then characterized STC2 expression in a series of human glioblastoma cell lines, including A172, LN18, LN229, U87MG, U251MG, and U373MG." (PMID 35790735, 2022). "These include previously identified HIF-1 target genes such as ANKRD37, STC-2, and STC-1, as well as COL5A1 induced by hypoxia in the ventricle, ZNF395 regulated by hypoxia in glioblastoma, and TMEM45 in hematopoietic stem cells." (PMID 25122487, 2014). "The results indicated that expression level of STC2 was significantly correlated with MMRs in almost all cancers except BLCA, cholangiocarcinoma (CHOL), DLBC, glioblastoma multiforme (GBM), KICH, LAML, and SARC." (PMID 35937984, 2022).
neuroblastoma (6 papers, 2011 to 2023). Neuroblastoma (NB) is the most common solid, extracranial childhood tumor. "In human neuroblastoma, the expression of STC2 is associated with clinical stages." (PMID 35501821, 2022). "STC2 expression is upregulated upon induction of hypoxic or endoplasmic reticulum (ER) stress in N2a neuroblastoma cells." (PMID 21545732, 2011).
Obesity (6 papers, 2017 to 2025). Accumulation of substantial excess body fat. "To determine hepatic STC2 expression in obesity-associated NAFLD, we evaluated its mRNA and protein levels in the livers of ob/ob mice." (PMID 30038584, 2018). "Herein, using a STC2‐/‐ mice that present enhanced post‐natal growth, then it can be also consider as an obesity murine model, we present evidence of a role of STC2 in the development of hyperglycaemia associated with a high‐fat food intake." (PMID 28990324, 2018). "Besides, hypertension and diabetes are linked by CXCL8, HLA-B, and KANSL1; diabetes and obesity are linked by TRIM26 and MMP8; hypertension and obesity are linked by PLA2G7, FSTL3, STC2, and BCL2A1." (PMID 36685671, 2023). "In addition, we observed that food intake and weight gain were also inhibited in C57BL/6 mice consuming a high-fat diet, suggesting a potential role of STC2 in combating obesity and metabolic disease." (PMID 29207625, 2017). "The STC2 gene has been implicated in cell proliferation in various cancers, postnatal growth, bone development and skeletal muscle growth in mice, as well as adiposity and obesity in nondiabetic humans." (PMID 40452020, 2025). "According to these results, STC2‐/‐ mice would represent a good experimental model of hyperglycaemia induced by a hypercaloric diet, and then it could be used as experimental model for establishing possible links between obesity and DM2 appearance." (PMID 28990324, 2018). "Summarizing, our result would indicate that STCs and particularly STC2 are a suitable marker of DM2 appearance and progression, and might be a linking protein between obesity and DM2." (PMID 28990324, 2018). "Notably, STC2 also played a role in adiposity and obesity in nondiabetic humans." (PMID 31931702, 2020).
rectal cancer (6 papers, 2021 to 2023). A primary or metastatic malignant neoplasm that affects the rectum. "It has been reported that STC2 expression is elevated in tumor tissues and serum of patients with rectal cancer, and that elevated STC2 expression in tumor tissues and serum correlates with patients’ tumor pathological stage and poor survival." (PMID 36685853, 2022). "The analysis of STC2 expression in rectal cancer tissues and cells showed that STC2 increased expression in tumor tissues and cells." (PMID 34249085, 2021). "In conclusion, lncRNA SNHG17 functions as an oncogenic lncRNA in rectal cancer by regulating the miR-361-3p/STC2 axis." (PMID 34249085, 2021). "Next, we showed that STC2 was a functional target of SNHG17 as STC2 depletion can reverse the effects of SNHG17 overexpression on rectal cancer cell proliferation." (PMID 34249085, 2021). "The upregulation status of stanniocalcin 2 (STC2) was also found in rectal cancer, and the knockdown of STC2 hinders cancer progression." (PMID 34249085, 2021). "Here, we also revealed that the high expression status of STC2 in rectal cancer, and the knockdown of STC2 can suppress rectal cancer cell proliferation." (PMID 34249085, 2021). "The analysis of STC2 expression in rectal cancer tissues and normal tissues using the IHC method and showed that the STC2 protein level was also increased in rectal cancer tissues compared with normal tissues." (PMID 34249085, 2021). "In the CCK-8 assay, the knockdown of STC2 reversed the stimulation effects of SNHG17 on rectal cancer cell proliferation (p < 0.001)." (PMID 34249085, 2021). "In addition, we found that increased SNHG17 expression could stimulate STC2 expression levels in rectal cancer cells (0.95 ± 0.12 vs. 4.35 ± 0.41 in SW837, 1.00 ± 0.13 vs. 5.36 ± 0.31 in SW1463, p < 0.001)." (PMID 34249085, 2021). "Our study also found that STC2 expression was up-regulated in COADREAD, COAD and READ, which may confirm STC2 serve as a potential tumor biomarker for the diagnosis and prognosis of rectal cancer." (PMID 36685853, 2022).
diabetes (5 papers, 2018 to 2025). "Recently, we also demonstrated reduced STC2 expression in platelets from type 2 diabetes mellitus patients (DM2)." (PMID 41155293, 2025). "Summarizing, we present evidence of the role of STCs, mainly STC2, as a possible early marker during development of diabetes mellitus." (PMID 28990324, 2018). "We have recently suggested that STC2 might be involved in the pathophysiology of type 2 diabetes mellitus, where STC2 is downregulated." (PMID 29628897, 2018). "On the other hand, stanniocalcin 2 (STC-2) has been depicted as an inhibitor of the proteolytic activity of PAPP-A, having been demonstrated multiple alterations of the PAPP-A/Stc-2 axis in a great variety of conditions, such as diabetes mellitus, cancer, and cardiovascular disorders." (PMID 33381575, 2020).
glioma (5 papers, 2019 to 2022). A benign or malignant brain and spinal cord tumor that arises from glial cells (astrocytes, oligodendrocytes, ependymal cells). "Under hypoxic conditions, enriched STC2 was identified from the exosome and soluble fractions of glioma cell lines." (PMID 34612765, 2021). "The hypoxia-induced glioma secretome analysis by LC-MS/MS reported that stanniocalcin 1 (STC1) and stanniocalcin 2 (STC2) have a role in the induction of glioma cell migration in a hypoxia-dependent manner." (PMID 31405033, 2019). "STC2 could form a histidine-rich glycoprotein/stanniocalcin-2 (HRG/STC2) complex with HRG to regulate murine glioma growth via modulation of anti-tumor immunity." (PMID 35937984, 2022). "Although it was unclear whether STC2 existed in the serum of glioma patients, it was secreted in the conditional medium of tumor cell lines." (PMID 34612765, 2021). "The colocalization of HRG and STC2 in gliomas may play a role for suppressing glioma growth by modulating tumor inflammation through monocyte infiltration and differentiation." (PMID 32498020, 2020).
hypertriglyceridemia (5 papers, 2018 to 2025). A laboratory test result indicating elevated triglyceride concentration in the blood. "First, overexpression of STC2 improved hepatic steatosis and hypertriglyceridemia in obese mice; here, we identified a rare variant (5:173,328,063:C:A) negatively associated with predicted PDFF and serum triglycerides." (PMID 40065360, 2025). "In obese mice, overexpression of STC2 significantly attenuated fatty liver and hypertriglyceridemia." (PMID 39415606, 2025). "STC2 ameliorated hepatosteatosis and hypertriglyceridemia in obese mice, mainly through activation of the STAT3 signaling pathway." (PMID 30038584, 2018). "Systemic administration of STC2 recombinant protein or adenovirus-mediated overexpression of STC2 markedly attenuated hepatosteatosis and hypertriglyceridemia in obese mice." (PMID 30038584, 2018). "Overexpression of STC2 significantly attenuated fatty liver and hypertriglyceridemia in obese mice through activation of the STAT3 signaling pathway." (PMID 30038584, 2018).
liver cancer (5 papers, 2020 to 2025). An epithelial or non-epithelial malignant neoplasm that arises from the liver. "Some studies have found a close relationship between STC2 mutations and the onset and prognosis of liver cancer, especially in terms of overall survival and disease-free survival of patients." (PMID 36685853, 2022). "We found two types of mutations and amplifications of STC2 in liver cancer, with missense mutations as the predominant type, which confirmed the role of STC2 mutation in liver cancer." (PMID 36685853, 2022). "In liver cancer, it was suggested that STC2 interacted with various factors to exert effects and more studies are needed to fully understand the role of STC2 in these complex networks." (PMID 34612765, 2021). "STC2 protein was a potential oncoprotein in the development and progression of liver cancer, thus being considered as a promising biomarker and molecular target for the anti-cancer therapy." (PMID 32579175, 2020). "Inhibiting STC2 overexpression may be a promising candidate for targeted liver cancer therapy." (PMID 39882072, 2024). "Spatial transcriptome analysis shows that STC2 and BIRC5 are mainly enriched in liver cancer cells and their mRNA and protein expression levels were greater in higher malignant HCC cell lines than in the lower ones." (PMID 40458412, 2025). "Differ from STC2 and BIRC5 which were mainly expressed in liver cancer cells, EPO and GLP1R did not exhibit specific expression in a certain cell type, which could potentially be attributed to the fact that EPO and GLP1R may not predominantly expressed in HCC cell lines." (PMID 40458412, 2025).
acute myeloid leukemia (4 papers, 2021 to 2025). Acute myeloid leukemia (AML) is a group of neoplasms arising from precursor cells committed to the myeloid cell-line differentiation. "The STC2 is positively correlated with TMB including CESC, acute myeloid leukemia (LAML), LUAD, prostate adenocarcinoma (PRAD), READ, THYM and negatively correlated with BRCA, and THCA." (PMID 40535801, 2025). "STC2 expression level was positively correlated with 60 ICP genes in most tumors, including HNSC, BLCA, acute myeloid leukemia (LAML), stomach adenocarcinoma (STAD), and uterine carcinosarcoma (UCS)." (PMID 35937984, 2022).